CLDN18 (claudin 18)
Diseases named in the same sentence as CLDN18 in open-access papers (continued):
Sharing a sentence is not in itself a finding about the gene and the disease.
adenoma (3 papers, 2022 to 2024). A neoplasm arising from the epithelium. "Five (26%) of such dysplastic growths (two CrD-associated flat conventional dysplasias, two CrD-associated non-conventional lesions and one Spo-SBA-associated conventional adenoma) showed CLDN18-positive cells." (PMID 35925388, 2022). "They found that 22.6% of hyperplastic polyps (n = 53), 1.6% of adenomas (n = 63), 35.5% of sessile serrated adenomas (n = 31), and 12.8% of traditional serrated adenomas expressed CLDN18." (PMID 38540693, 2024). "In MCN, 8 of 13 adenomas did not express or had weak expression for claudin-18, whereas all seven carcinomas showed strong claudin-18 expression." (PMID 37627123, 2023). "The expression of claudin-18 was similar to claudin-4, where one of three IPMN adenomas showed negative expressions of claudin-18, while seven of eight IPMN carcinomas strongly expressed claudin-18." (PMID 37627123, 2023).
dysplasia (3 papers, 2020 to 2025). A usually neoplastic transformation of the cell, associated with altered architectural tissue patterns. "In dysplasias, ten of 11 (91%) cases were positive for CDH17 and 6 of 11 (55%) were positive for CLDN18." (PMID 39164422, 2025). "Therefore, claudin-18 may affect the transdifferentiation of AECs through the WNT pathway, resulting in alveolar dysplasia." (PMID 36299696, 2022).
hepatocellular carcinoma (3 papers, 2022 to 2024). A malignant tumor that arises from hepatocytes. "We observed a significant upregulation of GYPA and CLDN18 in hepatocellular carcinoma tissues." (PMID 38774870, 2024). "Our findings indicated an upregulation of GYPA and CLDN18 mRNA levels in hepatocellular carcinoma tissues, with CLDN18 expression elevated in hepatocellular carcinoma cell lines and GYPA expression increased in most hepatocellular carcinoma cell lines." (PMID 38774870, 2024). "We initially compared the expression differences of GYPA and CLDN18 between human hepatocellular carcinoma and adjacent non-tumor tissues using immunohistochemistry staining." (PMID 38774870, 2024). "Subsequently, we assessed the differences in mRNA expression levels of GYPA and CLDN18 between human hepatocellular carcinoma and adjacent non-tumor tissues, as well as between normal liver cell lines and hepatocellular carcinoma cell lines." (PMID 38774870, 2024).
intraepithelial neoplasia (3 papers, 2020 to 2024). A precancerous neoplastic process that affects the squamous, glandular, or transitional cell epithelium without evidence of invasion. "In mouse models, Claudin 18 loss increased H+ leakage, inflammatory cell infiltration, and gastric metaplasia, resulting in intraepithelial neoplasia and invasive tumors." (PMID 32668412, 2020). "In gastrointestinal cancer, membrane-bound CLDN7 and CLDN18 were proven to offer reliable immunohistochemical markers for the diagnosis of pancreatic ductal neoplasia, and CLDN18 has high sensitivity and specificity for diagnosing biliary tract adenocarcinoma or intraepithelial neoplasia." (PMID 38731853, 2024).
atrophic gastritis (2 papers, 2014 to 2019). "CLDN18 knockout mice show prompted onset of atrophic gastritis by disrupted proton barrier with IL-1β upregulation." (PMID 31040910, 2019). "Moreover, targeted disruption of Cldn‐18 in mice resulted in abnormalities in gastric mucosa and atrophic gastritis via decreasing paracellular barrier against H+ in stomach epithelium." (PMID 24744879, 2014).
bile duct cancer (2 papers, 2018 to 2023). "For bile duct carcinoma, it was found that the knockdown of claudin-18 expression or an antibody specific to claudin-18 can significantly attenuate the proliferation, invasion and in vivo tumourigenesis of bile duct adenocarcinoma cells." (PMID 36969060, 2023).
bone metastasis (2 papers, 2022 to 2023). Transfer of a neoplasm from its primary site to bones. "Meanwhile, CLDN18 expression was significantly higher in patients with bone metastasis than in those without bone metastasis (p = 0.01)." (PMID 35053454, 2022).
celiac disease (2 papers, 2020 to 2024). An autoimmune genetic disorder with an unknown pattern of inheritance that primarily affects the digestive tract. "These metabolites and the capsular component increased the level of expression of genes coding for mucins, trefoil factor 1 (TFF1) and claudin 18 (CLDN18) that were found to be expressed at a lower rate in celiac disease organoids." (PMID 38396767, 2024).
Crohn disease (2 papers, 2022 to 2025). A gastrointestinal disorder characterized by chronic inflammation involving all layers of the intestinal wall, noncaseating granulomas affecting the intestinal wall and regional lymph nodes, and transmural fibrosis. "In addition, some cancer-adjacent dysplastic growths and foci of gastric-type metaplasia in Crohn’s disease-associated cases showed claudin-18 immunoreactivity." (PMID 35925388, 2022). "A fraction of small bowel adenocarcinomas, mainly sporadic or Crohn’s disease-associated, and often exhibiting a non-intestinal immunoprofile, expressed claudin-18, suggesting that claudin-18-directed targeted therapy is worth investigating in such cancers." (PMID 35925388, 2022).
edema (2 papers, 2022 to 2025). An abnormal accumulation of fluid beneath the skin, or in one or more cavities of the body. "Suppression of tight junction genes such as CLDN11, CLDN16, and CLDN18 suggests impaired epithelial barrier integrity, potentially enhancing vascular permeability and pulmonary edema, as reported in COVID-19-related lung injury." (PMID 41200555, 2025). "Especially in a model of hyperoxia-induced BPD, claudin-18 has been shown to possibly be involved in early pulmonary edema development and late alveolar development." (PMID 36299696, 2022).
glioblastoma (2 papers, 2023 to 2024). The most malignant astrocytic tumor (WHO grade IV). "In the TCGA pan-cancer cohort, PAAD, CRC, STAD, and LUAD expressed higher levels of CLDN18, whereas lower grade glioma (LGG), prostate adenocarcinoma (PRAD), glioblastoma multiforme (GBM), and ovarian serous cystadenocarcinoma (OV) had lower levels of CLDN18 expression." (PMID 39555091, 2024).
inflammatory bowel disease (2 papers, 2017 to 2022). A spectrum of small and large bowel inflammatory diseases of unknown etiology. "CLDN18, which is expressed in the human gastrointestinal tract, is a key gene in the development of inflammatory bowel disease." (PMID 29209594, 2017).
kidney cancer (2 papers, 2017 to 2022). Primary or metastatic malignant neoplasm involving the kidney. "An overview of the expression features of all the claudin family genes in three kinds of kidney cancer revealed that nearly all the genes were downregulated in ccRCC tumors, with the exception of claudin 18 in ccRCC." (PMID 36479115, 2022). "Pairwise CLDN biomarker AUC comparisons (heatmap), across 12 tumor types (The Cancer Genome Atlas; TCGA data), showed that CLDN1 could readily distinguish colon from kidney, brain, lung, and ovary cancers, while both CLDN1 and CLDN4 (but not CLDN18) could distinguish brain from kidney cancer." (PMID 29050243, 2017).
liver cancer (2 papers, 2023 to 2024). An epithelial or non-epithelial malignant neoplasm that arises from the liver. "Further experimental validation in tissue and cell samples demonstrated that CLDN18 was upregulated in cancer tissues and cells, and knocking down CLDN18 inhibited the malignant behavior of liver cancer cells." (PMID 38774870, 2024). "Validation through tissue and cell samples confirmed that GYPA and CLDN18 were upregulated in liver cancer tissues and cells." (PMID 38774870, 2024). "In a previous study, we found that CLDN18 is highly expressed in liver cancer tissues as well as in the PBMCs of the patients." (PMID 37438735, 2023). "Furthermore, in vitro knockdown of CLDN18 inhibited the malignancy capabilities of liver cancer cells." (PMID 38774870, 2024). "This suggests that CLDN18, as an immunological target, may not only confer resistance to ADCP in liver cancer cells but also enhance their malignancy." (PMID 38774870, 2024).
melanoma (2 papers, 2022 to 2023). A malignant, usually aggressive tumor composed of atypical, neoplastic melanocytes. "Next generation sequencing found that GRIN2A mutation was related to CLDN18.2 expression in advanced gastric SRCC, which was frequently found in melanoma and induced the loss of tumor suppressor function." (PMID 35811317, 2022). "We next determined the in vitro killing activity of CAR-T cells against both Panc02 cells and B16F10 mouse melanoma cells expressing either CLDN18.2 (Panc02-claudin 18.2 cell and B16F10-claudin 18.2 cell) or CLDN18.1 (Panc02-claudin 18.1 cell and B16F10-claudin 18.1 cell)." (PMID 37564658, 2023).
metastasis (2 papers, 2023). The spread or migration of cancer cells from one part of the body (where they first appeared) to another. "Additionally, lung metastasis tended to be more frequent in the CLDN18-negative group, although the difference was not significant." (PMID 37629433, 2023).
metastatic disease (2 papers, 2024 to 2025). "Here, the authors characterized mutations in a cohort of matched primary and metastatic disease, and found mutations, including in CLDN18, could predict treatment response to paclitaxel." (PMID 38704377, 2024). "Moreover, novel therapeutic platforms such as CAR-T cells targeting claudin 18.2 or other gastrointestinal-specific antigens are being actively explored in metastatic disease, showing early signs of safety and activity." (PMID 41300970, 2025).
pancreatic ductal adenocarcinoma (2 papers, 2023 to 2025). An infiltrating adenocarcinoma that arises from the epithelial cells of the pancreas. "Interestingly, one study demonstrated increased OS rates in surgically resected pancreatic ductal adenocarcinomas (PDAC) with high CLDN18 expression." (PMID 39731204, 2025).
small bowel adenocarcinomas (2 papers, 2022 to 2025). "The immunohistochemical expression of claudin-18 (clone 43-14A) was assessed in 81 small bowel adenocarcinomas of diverse aetiologies and correlated with several clinico-pathologic features and patient survival." (PMID 35925388, 2022). "This is the first study focusing on claudin-18 expression in small bowel adenocarcinomas." (PMID 35925388, 2022).
virus infection (2 papers, 2017 to 2025). "The gene expression detection results showed that both ceRNA-chr19 and CLDN18 were up-regulated post virus infection, and circRNA-chr19 expression paralleled CLDN18 expression under the stimulation of virus reproduction." (PMID 29209594, 2017).
acid reflux (1 paper, 2020). "Claudins are key components to epithelial tight junctions, and claudin-18 has been reported to be highly expressed in BE and may be associated with increased resistance to acid reflux." (PMID 33512805, 2020).
adenosquamous carcinoma (1 paper, 2025). A carcinoma composed of malignant glandular cells and malignant squamous cells. "Of these, five cases displayed a random pattern of heterogeneity, one case showed an invasive-front pattern, and in one case of adenosquamous carcinoma, CLDN18 expression was restricted to the adenocarcinoma component." (PMID 40205072, 2025).
airway hyperresponsiveness (1 paper, 2017). "Furthermore, claudin-18–null mice had significantly higher serum IgE levels and increased airway responsiveness after intranasal Aspergillus species sensitization, suggesting loss of claudin-18 can promote sensitization and airway hyperresponsiveness." (PMID 28583446, 2017).
atherosclerosis (1 paper, 2025). A disease characterized by the build-up of fatty material and calcium deposition in the arterial wall resulting in partial or complete occlusion of the arterial lumen. "Our observation of CLDN18 upregulation in CAD patients aligns with studies highlighting endothelial tight junction dysregulation in atherosclerosis." (PMID 41226477, 2025).
autoimmune gastritis (1 paper, 2023). Inflammation of the body fundic mucosa of the stomach. "Immunohistochemical analyses targeting claudin 18 revealed that 18.9% of autoimmune gastritis cases with intestinal metaplasia manifest positive staining, in contrast to 71.4% in those without autoimmune gastritis, indicating the distinct nature of intestinal metaplasia in autoimmune gastritis." (PMID 37504250, 2023).
breast tumours (1 paper, 2015). "We found that all ten EMT-related genes were frequently methylated in primary breast tumours, i.e. CLDN18 (100 %), KRT85 (100 %), MIR127 (100 %), MIR433 (100 %), MIR23b (60 %), KRT83 (100 %), MST1R (60 %), BVES (60 %), CLDN6 (50 %) and HOXD10 (55 %)." (PMID 26052355, 2015).
chronic pancreatitis (1 paper, 2011). A chronic inflammatory process causing damage and fibrosis of the pancreatic parenchyma. "We also determined whether pancreatic lesions in CK19CreERT; LSL-KrasG12D mice expressed claudin-18, which is highly expressed in PanINs and PDAC but not in normal ducts or reactive ducts that are commonly seen in chronic pancreatitis." (PMID 21311774, 2011).
dermatitis (1 paper, 2009). An inflammatory process affecting the skin. "While the distribution of Cldn6, Cldn11, Cldn12 and Cldn18 corresponded to the expanded suprabasal compartment of the dermatitis-affected Inv-Cldn6-CΔ196 epidermis, immunostaining was less intense and membranous localization less evident in lower suprabasal layers." (PMID 19915705, 2009).
Ebola (1 paper, 2017). "Interestingly, the discovery of circRNA-chr19 as a ceRNA for CLDN18 could increase the reliability of the prediction results, including ceRNA prediction and network construction, allowing them to be used as important tools to further explore potential targets and therapeutic agents in Ebola therapy." (PMID 29209594, 2017).
endometrial cancer (1 paper, 2024). Primary or metastatic malignant neoplasm involving the endometrium (mucous membrane that lines the endometrial cavity). "An interesting finding is the over-expression of CLDN18 which has been demonstrated to activate metastasis and proliferation for other cancers but not endometrial cancers." (PMID 38408048, 2024).
endothelial dysfunction (1 paper, 2025). In vascular diseases, endothelial dysfunction is a systemic pathological state of the endothelium (the inner lining of blood vessels) and can be broadly defined as an imbalance between vasodilating and vasoconstricting substances produced by (or acting on) the endothelium. "The set includes genes such as CLDN18, NOS2, SLC4A1, CA4, COL17A1, and SP7, many of which have been implicated in vascular inflammation, endothelial dysfunction, and extracellular matrix remodelling." (PMID 41226477, 2025).
Fanconi anemia (1 paper, 2023). Fanconi anemia (FA) is a hereditary DNA repair disorder characterized by progressive pancytopenia with bone marrow failure, variable congenital malformations and predisposition to develop hematological or solid tumors. "KEGG pathway analysis showed that CLDN18 co-expressed genes were mainly enriched in DNA replication, homologous recombination, cell cycle and Fanconi anemia pathways." (PMID 37438735, 2023). "KEGG pathway analysis further showed that CLDN18 and its co-expressed genes are mainly enriched in DNA replication, homologous recombination, cell cycle and Fanconi anemia pathways." (PMID 37438735, 2023).
Hypercholesterolemia (1 paper, 2025). An increased concentration of cholesterol in the blood. "In the validation cohort, CLDN18 expression was found to be significantly (p < 0.05) associated with hypertriglyceridemia and hypercholesterolemia, but this effect was restricted to patients with obstructive CAD." (PMID 41226477, 2025).
idiopathic pulmonary fibrosis (1 paper, 2022). Idiopathic pulmonary fibrosis (IPF) is a nonneoplastic pulmonary disease that is characterized by the formation of scar tissue within the lungs in the absence of any known cause. "A recent meta-analysis using miRNA and gene expression profiles downloaded from the Gene Expression Omnibus database identified differentially expressed genes and miRNAs between an idiopathic pulmonary fibrosis (IPF) group and a normal group, and CLDN18 was identified as a potential IPF biomarker." (PMID 35642043, 2022).
invasive carcinoma (1 paper, 2025). A carcinoma that is not confined to the epithelium, and has spread to the surrounding stroma. "Three of 25 (12%) CD-SBNs (1 conventional type invasive carcinoma and 2 conventional type dysplasias; 1 dysplasia was adjacent to SATB2 positive invasive carcinoma) were SATB2 positive and all SATB2-positive CD-SBNs showed CDH17 expression, whereas no CLDN18 expression was identified." (PMID 39164422, 2025).
invasive ductal breast carcinoma (1 paper, 2021). The most common type of invasive breast carcinoma, accounting for approximately 70% of breast carcinomas. "In the BC dataset of Turashvili’s study, CLDN18 was downregulated in invasive ductal breast carcinoma with a fold change of –2.301 (p = 1.89E-04) and CLDN23 was downregulated in invasive lobular breast carcinoma with a fold change of –3.776 (p = 0.025)." (PMID 33714203, 2021).
lung injury (1 paper, 2015). "Claudin 18 (Cld18; up-regulated 9-fold), a gene associated with the barrier function of epithelial tight junctions in the lung has been reported to be increased during acute lung injury." (PMID 25710175, 2015).
mucinous ovarian cancer (1 paper, 2022). An invasive malignant neoplasm that arises from the ovary and is characterized by the presence of malignant epithelial cells that contain intracytoplasmic mucin and may resemble the epithelial cells of the endocervix or gastrointestinal tract. "CLDN18 has recently been established as a normal gastric tissue marker; however, the presence of a splice variant has been documented in patients with mucinous ovarian cancers, a rare subtype with a poor outlook." (PMID 36233808, 2022).